CSGALNACT1 (chondroitin sulfate N-acetylgalactosaminyltransferase 1)
Description:
Transfers 1,4-N-acetylgalactosamine (GalNAc) from UDP-GalNAc to the non-reducing end of glucuronic acid (GlcUA). Required for addition of the first GalNAc to the core tetrasaccharide linker and for elongation of chondroitin chains. Important role in chondroitin chain biosynthesis in cartilage formation and subsequent endochondral ossification. Moreover, is involved in the metabolism of aggrecan (By similarity).
Synonyms: CsGalNAcT-1; CHGN; FLJ11264; ChGn-1; SDJLABA; beta4GalNAcT
Tractability: Antibody: UniProt predicts a signal peptide or a membrane-spanning region. PROTAC: its protein half-life has been measured.
Target class: Enzyme; Transferase
Gene: Protein-coding gene on chromosome 8 (19,404,156 to 19,758,029, reverse strand). Ensembl gene ENSG00000147408.
Subcellular location: Golgi apparatus, Golgi stack membrane
Subcellular location (Human Protein Atlas): Cytosol; Golgi apparatus
Pathways (Reactome):
Metabolism: CS-GAG biosynthesis
Gene Ontology:
Molecular function: acetylgalactosaminyltransferase activity; glucuronosyl-N-acetylgalactosaminyl-proteoglycan 4-beta-N-acetylgalactosaminyltransferase activity; glucuronosyltransferase activity; glucuronylgalactosylproteoglycan 4-beta-N-acetylgalactosaminyltransferase activity; peptidoglycan glycosyltransferase activity; metal ion binding
Biological process: chondroitin sulfate proteoglycan biosynthetic process; UDP-glucuronate metabolic process; UDP-N-acetylgalactosamine metabolic process; dermatan sulfate proteoglycan biosynthetic process; heparan sulfate proteoglycan biosynthetic process; heparin proteoglycan biosynthetic process; proteoglycan biosynthetic process
Cellular component: Golgi membrane; Golgi apparatus; Golgi cisterna membrane
Genetic constraint (gnomAD): Loss-of-function variants: 52 observed, 52.13 expected, observed/expected ratio (o/e) 1, 90% interval 0.8 to 1.26. The synonymous counts are far from expectation, so gnomAD's model fits this gene poorly and the ratio says little. Missense variants: 929 observed, 709.71 expected, observed/expected ratio (o/e) 1.31, 90% interval 1.24 to 1.38. Synonymous variants: 341 observed, 267.35 expected, observed/expected ratio (o/e) 1.28, 90% interval 1.17 to 1.39.
Gene-disease validity (ClinGen):
ClinGen rates the evidence that CSGALNACT1 causes each of these diseases.
skeletal dysplasia, mild, with joint laxity and advanced bone age (autosomal recessive): Moderate.
Homologues: Orthologues: chimpanzee CSGALNACT1 (99% identical), macaque CSGALNACT1 (98% identical), guinea pig CSGALNACT1 (92% identical), mouse Csgalnact1 (91% identical), rat Csgalnact1 (91% identical), dog CSGALNACT1 (90% identical), pig CSGALNACT1 (87% identical), rabbit CSGALNACT1 (86% identical), tropical clawed frog csgalnact1 (79% identical), zebrafish csgalnact1a (71% identical), zebrafish csgalnact1b (44% identical), Drosophila melanogaster Csgalnact (38% identical). Paralogues in human: CSGALNACT2 (61% identical), CHSY3 (30% identical), CHSY1 (29% identical), B4GALNT3 (20% identical), B4GALNT4 (20% identical), CHPF2 (18% identical), CHPF (18% identical).
Diseases named in the same sentence as CSGALNACT1 in open-access papers:
CSGALNACT1 is named in the same sentence as 29 diseases in open-access papers, as found by Europe PMC text mining. Sharing a sentence is not in itself a finding about the gene and the disease. The quoted sentences say what the papers report.
myeloma (3 papers, 2013 to 2021). "Highest RNA expression among different tissue types tested was identified in the thyroid and placenta and statistical network reconstruction on expression data of multiple myeloma identified that high expression of CSGALNACT1 was associated with favorable prognosis." (PMID 25923053, 2015). "A most interesting candidate for further investigation includes CSGALNACT1 which encodes a protein involved in the synthesis of chondroitin sulphate, a component of Syndecan-1 (CD138) involved in myeloma pathogenesis." (PMID 24376673, 2013). "Another interesting candidate for further investigation is CSGALNACT1 which encodes a protein involved in the initial synthesis of chondroitin sulphate, a component of Syndecan-1 (CD138), also known as a central player in multiple myeloma pathogenesis." (PMID 24376673, 2013). "Studies showed that in myeloma, CSGALNACT1 was under-expressed in MM cells compared to normal bone marrow plasma cells, which suggest that the overexpression of CSGALNACT1 is associated with a good prognosis." (PMID 34917133, 2021).
prostate carcinoma (3 papers, 2016 to 2024). A carcinoma that arises from epithelial cells of the prostate gland. "On the contrary, CSGALNACT1 could act as a risk factor in breast cancer and prostate cancer." (PMID 33344452, 2020). "Decreased expression of CSGALNACT1 can increase the numbers of dead and apoptotic cells and significantly decrease cell viability in prostate cancer cells." (PMID 38082211, 2024). "Of 31 reciprocally-regulated glycosylation enzymes, a set of 8 (GALNT7, ST6GalNAc1, GCNT1, UAP1, PGM3, CSGALNACT1, ST6GAL1 and EDEM3) were significantly up-regulated in clinical prostate carcinoma." (PMID 27428423, 2016).
breast carcinoma (2 papers, 2020 to 2023). "Variants in BICD2 (six cases), FBN1 (four cases), CSGALNACT1 (one case), and ZNF841 (one case) were observed in at least one UKBiobank breast cancer case, but not in any controls." (PMID 38136396, 2023).
depression (2 papers, 2016 to 2017). "This network consisted of a number of molecules previously reported to be associated with depression (according to a PubMed search), such as CYP3A5, VAMP2, CSGALNACT1, CASP8, CRHR2, PKD2, and OXT." (PMID 26728011, 2016). "Another target gene, CSGALNACT1 (hsa_circRNA_001781), which was downregulated in patients with T2DM with depression, was reported to be related to the antidepressant response." (PMID 28779132, 2017). "In addition, FKBP4, PKD2, CSGALNACT1, and VAMP2 have been reported in relation to depression (or mood disorders)." (PMID 26728011, 2016).
osteoarthritis (2 papers, 2012 to 2017). A noninflammatory degenerative joint disease occurring chiefly in older persons, characterized by degeneration of the articular cartilage, hypertrophy of bone at the margins and changes in the synovial membrane. "There are inherited diseases in humans associated with mutations in the CSGALNACT1 gene, and a decrease in chondroitin sulfate is associated with osteoarthritis in humans." (PMID 29287114, 2017). "CS is one of the major components of articular cartilage, and Csgalnact1-null mice exhibit some osteoarthritis-like changes in cartilage, such as a decreased level of aggrecan and link protein 1, a rapid catabolism of aggrecan, and abnormally aggregated and disarranged type-II collagen fibers." (PMID 22952769, 2012).
papillary thyroid carcinoma (2 papers, 2020 to 2025). "This study identifies CSGALNACT1 as an epithelial-specific gene with independent prognostic significance in papillary thyroid carcinoma." (PMID 40950406, 2025). "In this study, we systematically integrated single-cell and bulk transcriptomic data to construct a prognostic model for papillary thyroid carcinoma (PTC) and identified CSGALNACT1 as a novel epithelial-specific oncogenic regulator." (PMID 40950406, 2025).
respiratory failure (2 papers, 2020 to 2021). The significant impairment of gas exchange within the lungs resulting in hypoxia, hypercarbia, or both, to the extent that organ tissue perfusion is severely compromised. "In rats, reduced levels of CSGALNACT1 may cause post-natal lethality due to respiratory failure, mild dwarfism and the cartilage has an abnormality of endochondral ossification." (PMID 32493207, 2020). "Approximately 80% of Col2a1-Cre; Csgalnact1flox/—; Csgalnact2flox/— double cKO mice, which were deficient in both Csgalnact1 and Csgalnact2 in chondrocytes, immediately died after birth because of respiratory failure, and the remaining ∼20% of the double KO mice could start spontaneous respiration." (PMID 34901009, 2021). "Mice with double KO of Csgalnact1 and Csgalnact2 died during the postnatal stage due to respiratory failure." (PMID 34901009, 2021).
cholangiocarcinoma (1 paper, 2022). A carcinoma that arises from the intrahepatic biliary tree (intrahepatic cholangiocarcinoma) or from the junction, or adjacent to the junction, of the right and left hepatic ducts (hilar cholangiocarcinoma). "We found that the change in expression of CSGALNACT1 in FLC (relative to corresponding nonmalignant tissue) is second only to cholangiocarcinoma (CCA)." (PMID 36923282, 2022).
emphysema (1 paper, 2023). "The most strongly upregulated gene in LMSCs from emphysema patients was CSGALNACT1, which encodes chondroitin sulfate N-acetylgalactosaminyltransferase-1 (CSGalNAcT-1)." (PMID 36681830, 2023).
multiple sclerosis (1 paper, 2023). A progressive autoimmune disorder affecting the central nervous system resulting in demyelination. "CSGALNACT1 is an enzyme involved in the biosynthesis of alternative forms of glycosaminoglycans, namely chondroitin sulfate, linked to B cell activity, as well as multiple sclerosis progression." (PMID 36725857, 2023).
skeletal dysplasia (3 papers, 2018 to 2021). Any Mendelian diseases that affects growth and development of the skeleton. "Mutations in CSGALNACT1 are associated with a mild skeletal dysplasia and joint laxity." (PMID 34441372, 2021). "Biallelic loss-of-function mutations in CSGALNACT1 gene results in reduced CSGalNAcT-1 activity leading to altered levels of chondroitin, dermatan, and heparan sulphate and cause a mild skeletal dysplasia with joint laxity and advanced bone age, CSGALNACT1-CDG." (PMID 34441372, 2021). "Contrary to PMM2-CDG, skeletal dysplasia was well characterized in other CDGs, including ALG12-CDG, ALG3-CDG, ALG9-CDG, ALG6-CDG, PGM3-CDG, CSGALNACT1-CDG, SLC35D1-CDG and TMEM165-CDG." (PMID 34441372, 2021). "Contrary to PMM2-CDG, all remaining CDG, including ALG12-CDG, ALG3-CDG, ALG9-CDG, ALG6-CDG, PGM3-CDG, CSGALNACT1-CDG, SLC35D1-CDG and TMEM-165, are characterized by well-defined skeletal dysplasia." (PMID 34441372, 2021). "There is a group of CDGs, including ALG12-CDG, ALG3-CDG, ALG9-CDG, ALG6-CDG, PGM3-CDG, CSGALNACT1-CDG, SLC35D1-CDG, and TMEM-165 with well-defined skeletal dysplasia." (PMID 34441372, 2021). "Two of the glycosylation defects, TMEM165-CDG and CSGALNACT1-CDG, are characterized by skeletal dysplasia and abnormal cartilage development." (PMID 34441372, 2021).
tumor (3 papers, 2022 to 2025). "Together, these findings highlight CSGALNACT1 as a key regulator of tumor cell proliferation and a potential driver of malignant phenotypes." (PMID 40950406, 2025). "Functional analysis showed that CSGALNACT1 promoted tumor cell proliferation, suggesting that it may have a previously unrecognized oncogenic role." (PMID 40950406, 2025). "Sodium selenite treatment upregulated pro-apoptotic, apoptotic, and tumor suppressor genes such as ATF3, FOSB, GADD45B, DUSP8 and ACHE, and downregulated tumor cell survival genes such as SCD, LRP1, RAB31, SRPX2, PDK1 and CSGALNACT1." (PMID 36059619, 2022).
cancer (1 paper, 2022). A tumor composed of atypical neoplastic, often pleomorphic cells that invade other tissues. "Our finding that CSGALNACT1 and VCAN expression levels in FLC are most similar to that of CCA suggests potential mechanistic parallels between the two cancer types in terms of fibrosis." (PMID 36923282, 2022). "Next, we sought to compare the expression of CSGALNACT1 and VCAN in FLC with other cancer types." (PMID 36923282, 2022).
CSGALNACT1 also shares sentences with these, for which no sentence is quoted: multiple myeloma (2 papers); cardiovascular diseases (1); colon cancer (1); diabetic neuropathy (1); dyslipidemia (1); Hyperglycemia (1); immune disease (1); intervertebral disc degeneration (1); ischemia (1); mood disorder (1); neurodegenerative disease (1); Obesity (1); oral squamous cell carcinoma (1); psychiatric disorder (1); thyroid cancer (1); type 2 diabetes (1).